CDK5 (cyclin dependent kinase 5)
Diseases named in the same sentence as CDK5 in open-access papers (continued):
Sharing a sentence is not in itself a finding about the gene and the disease.
neurodegenerative disease (continued). "Moreover, dysregulated Cdk5/calpain signalling pathway is also implicated in the development and progression of many neurodegenerative diseases." (PMID 38842132, 2024). "So, the identification of Cdk5 as a kinase that is mainly active in post-mitotic neurons has, not surprisingly, drawn the interest of many researchers, especially with Cdk5 also being linked to the neurofibrillary tangles seen in neurodegenerative diseases." (PMID 39235580, 2024). "CDK5 overactivation causes neuronal death in many neurodegenerative diseases, including HD41." (PMID 34489447, 2021). "Studies suggested that CDK5 was also implicated in neurodegenerative diseases." (PMID 31878035, 2019). "Indeed, some of the drugs or their targets, for example, tretinoin targeting RAR genes and GW‐8510 targeting CDK2 and CDK5, were previously linked to neuroprotective functions or neurodegenerative diseases." (PMID 29959820, 2018). "Moreover, some aggregation-prone proteins linked to neurodegenerative diseases can enhance the activity of Cdk5 towards Acinus, thereby reducing their own accumulation through elevated autophagy." (PMID 29227247, 2017). "p25 is an aberrant cyclin-dependent kinase 5 (Cdk5) activator generated from calpain-mediated cleavage of the Cdk5 activator p35 under neurotoxic conditions, and p25/Cdk5 is a proline-directed serine/threonine kinase implicated in several neurodegenerative diseases, including AD." (PMID 26317805, 2015). "Moreover, altered Cdk5 activity has been associated with many neurodegenerative diseases, which is mainly regulated by the increased proteolysis of p35 into p25, with a subsequent increased Cdk5 kinase activity." (PMID 24495352, 2014). "In addition, the deregulation of CDK5 activity is associated with neuronal death in neurodegenerative diseases." (PMID 25177270, 2014). "The suppression of neuroinflammation in Cdk5 cKO mice ameliorates gliosis and neuronal loss, thus suggesting the potential beneficial effects of the PPARγ agonist pioglitazone for the treatment for neurodegenerative diseases." (PMID 24495352, 2014). "Thus, the hyperactivation of Cdk5 is associated with neurodegenerative diseases." (PMID 38233717, 2024). "For instance, CDK5 plays a prominent role in neural development and in neurodegenerative diseases, like Alzheimer’s, Parkinson’s, and ALS." (PMID 39800748, 2025). "In the “Alzheimer’s/Neurodegeneration” cluster, the most significantly enriched pathways included “amyloid fiber formation”, “neurodegenerative diseases”, and “deregulated CDK5 triggers multiple neurodegeneration”." (PMID 40993111, 2025). "The applications of CDK5 inhibitors in CDK5 related neurodegenerative diseases have been drawing a lot of attention." (PMID 40565229, 2025). "Significantly, the KSPXK motifs within NF-M/H were hyperphosphorylated in the brains of AD patients, which further tied Cdk5 with neurodegenerative diseases." (PMID 39235580, 2024). "As described, research into Cdk5 and its role in neurodegenerative diseases were a major part of Harish’s research, but Cdk5 can be characterized as a ‘two-faced’ kinase in that its normal physiological activity is also important for neuronal survival." (PMID 39235580, 2024). "When 246 was assessed against neurodegenerative disease targets casein kinase 1 (CK1δ) and cyclin-dependent kinase 5 (CDK5), it was found to exhibit activity against CK1δ with IC50 = 3 μM." (PMID 39274880, 2024). "An interest in Cdk5 and its role in neurodegenerative diseases like AD would essentially from then on became a major focus of Harish Pant’s research." (PMID 39235580, 2024). "In neurodegenerative diseases, p25 formation is crucial for CDK5 deregulation due to its long half-life and by mislocalizing active CDK5 to the cytoplasm and nucleus." (PMID 37993880, 2023). "A study confirmed that both GSK3β and CDK5 have roles in neurodegenerative diseases where neuroinflammation takes a role." (PMID 37638222, 2023).
neurodegenerative disease (continued). "In this review, we focus on the regulatory mechanisms of Cdk5 and its roles in a series of common neurological disorders such as neurodegenerative diseases, stroke, anxiety/depression, pathological pain and epilepsy." (PMID 36438186, 2022). "Ningalins act as potent inhibitors against the HIV-1 virus and kinases related with neurodegenerative diseases (CDK5, GSK3b, CD1d)." (PMID 36662210, 2022). "Because of its extensive and crucial roles in nervous system, the dysfunction of Cdk5 is critically involved in numerous neurological disorders such as neurodegenerative diseases, stroke, psychiatric disorders, pathological pain, epilepsy and so on." (PMID 36438186, 2022). "In view of these findings, compound 3g can be considered a promising biased ligand to investigate the role of the 5-HT6R-elicited Gs and Cdk5 signaling pathways in neurodegenerative diseases." (PMID 36671397, 2022). "The abnormal activity of CDK5/p25 can elicit neurological abnormalities and a variety of neurodegenerative diseases." (PMID 36703741, 2022). "Cdk5-p35-mediated Acn-S437 phosphorylation alleviates proteostatic stress in Drosophila models of neurodegenerative diseases." (PMID 35037620, 2022). "Cyclin-dependent kinase 5 (Cdk5) is considered as a promising target in the drug design field for its role in the progression of neurodegenerative diseases such as AD and PD, as well as in the development and progression of a variety of tumors." (PMID 36142566, 2022). "Modulating the aberrant activity of Cdk5 has attracted attention as a therapeutic target for neurodegenerative diseases." (PMID 34814918, 2021). "Hyperactivation of Cdk5 appears to be a common theme among different neurodegenerative diseases, and blocking Cdk5 hyperactivity attenuates disease progression." (PMID 34814918, 2021). "CKD5 is a versatile kinase showing a pivotal role in modulating the function of postmitotic neurons in the developing CNS; the dysregulation of CDK5 is involved in the pathology of neurodegenerative diseases, such as AD, ALS, and IS." (PMID 34035826, 2021). "Emerging evidence links Cdk5 hyperactivity to excessive mitochondrial fission under pathological conditions, such as neurotoxic insults and neurodegenerative diseases." (PMID 34814918, 2021). "It seems likely that in addition to development and normal physiology of the nervous system and pathogenesis of neurodegenerative diseases, CDK5 plays distinct roles in physiology and pathogenesis of several different tissues." (PMID 31910742, 2020). "Accordingly, the targeting of Cdk5 activity has been suggested as a treatment strategy for a list of neurodegenerative diseases." (PMID 32046281, 2020). "Depending on its cofactor, CDK5 in the brain phosphorylates targets involved in neurodegenerative diseases (e.g. Tau, MAP1B), neuronal migration (e.g. DCX), and synaptic signaling (e.g. Cav2.2, Dynamin1, NR2A, DARPP-32)." (PMID 31687929, 2019). "Inhibition of overactivated CDK5 showed a neuroprotective effect against neurodegenerative diseases in a zebrafish model." (PMID 31395805, 2019). "CDK5 hyperactivation leads to neuronal death under the accumulation of amyloid β peptides and is widely believed to act as molecular pathogenesis of neurodegenerative diseases." (PMID 31395805, 2019). "The CDK5–p35 complex has essential roles in the regulation of central nervous system (CNS) development and neurodegenerative diseases." (PMID 31395805, 2019). "Deregulation of cyclin-dependent kinase 5 (Cdk5) is believed to play an important role in neurodegenerative diseases including PD." (PMID 29910724, 2018). "Cdk5/p25 complex more widely distributes in cytosol and hyperphosphorylates more substrates related to the pathogenesis of neurodegenerative disease including PD." (PMID 29910724, 2018). "In the context of neurodegenerative diseases, much interest has been focused on the aberrant activation of Cdk5." (PMID 29227247, 2017).
neurodegenerative disease (continued). "This theory would be consistent with findings that CDK5 expression levels are increased in certain neurodegenerative diseases, and that it is the aberrant CDK5 activity that leads to neurite collapse and death." (PMID 28077789, 2017). "One additional target for c-Abl deserving to be mentioned here is the cyclin-dependent kinase 5 (Cdk5) that is highly expressed in brain neurons and shown to be activated in neurodegenerative diseases including PD." (PMID 27833551, 2016). "Cdk5 has been proposed to play a key role in neurodegenerative diseases primarily through a cytoplasmic mechanism." (PMID 24662752, 2014). "Especially that is relevant for CDK5, which is involved in neurodegenerative diseases and CDK9, involved in viral replication." (PMID 25349887, 2014). "There is, however, growing need for CDK5 specific inhibitors to treat various neurodegenerative diseases." (PMID 24058495, 2013). "There is a particular demand for CDK5 specific inhibitors to treat various neurodegenerative diseases." (PMID 24058495, 2013). "A growing body of evidence demonstrates the action of Cdk5 in neuronal maturation and structural plasticity, with implications for disorders of neural activity and neurodegenerative disease." (PMID 25364642, 2012). "It is known that p25 activates Cdk5 more efficiently and results in deleterious effects on neurons in many neurodegenerative diseases." (PMID 22870316, 2012). "Drawing a parallel to the activation of GSK3β and CDK5 in neurodegenerative diseases, particularly the hyperphosphorylation of tau in AD, it is plausible that synphilin-1 may also undergo hyperphosphorylation in PD." (PMID 40869369, 2025). "Overall, these data support the primary role of CDK5 in neurodegenerative diseases." (PMID 39800748, 2025). "However, small peptides which block Cdk5/p25 have proven in preclinical studies for the management of stroke and neurodegenerative diseases." (PMID 38842132, 2024). "Understanding of the exact position of Cdk5 in the deleterious feed‐forward loop critical for development and progression of neurodegenerative diseases may help designing successful therapeutic strategies of several fatal neurodegenerative diseases." (PMID 38842132, 2024). "A key therapeutic strategy to treat neurodegenerative diseases would thereby involve finding a means to interfere with the pathological activity of Cdk5 by blocking its interaction with p25 while still maintaining its normal neuronal functions when complexed to p35." (PMID 39235580, 2024). "Abnormal Cdk5 signalling contributes to dysfunction of individual proteins and has a substantial role in either direct or indirect interactions of proteins common to, and critical in different neurodegenerative diseases." (PMID 38842132, 2024). "Given the ADMET properties of BCI, it could constitute a promising lead compound for the development of selective CDK5 inhibitors in this neurodegenerative disease." (PMID 37760412, 2023). "In addition, they also show potent inhibition against kinases related with neurodegenerative diseases, such as cyclic-dependent kinase 5 (CDK5), glycogen synthase kinase 3b (GSK3b) and casein kinase I (CD1d)." (PMID 36662210, 2022). "Cyclin-dependent kinase 5 (Cdk5), a member of the proline-directed serine/threonine cyclin-dependent kinase family, largely controls a number of neuronal functions and is known to be a major player in the pathogenesis of neurodegenerative diseases." (PMID 35203613, 2022). "Achieving systemic applicability may be considered a step forward toward the testing of Cdk5 inhibitors to treat neuropsychiatric and neurodegenerative diseases." (PMID 35645825, 2022). "Moreover, we discuss evidence underscoring aberrant Cdk5 activity as a common theme observed in many neurodegenerative diseases." (PMID 34814918, 2021).
neurodegenerative disease (continued). "Only low cytotoxicities against human, bacterial, and fungal cell lines were observed, whereas the ningalins 183 and 184 showed moderate inhibition of the kinases CK1δ, CDK5, and GSK3β, potential targets for the treatment of neurodegenerative diseases (IC50 values between 1.6 μM and 10.9 μM)." (PMID 34564176, 2021). "CDK5 signaling plays a significant role in neuronal function, namely the control of cytoskeletal architecture and dynamics, axonal guidance, neuronal migration, and cell adhesion, and participates in the pathological changes in neurodegenerative diseases." (PMID 32708879, 2020). "For example, the membrane-bound protein p35 has been demonstrated to be a major substrate exclusively regulated by CAPNs and can further amplify neurotoxic insults or oxidative stress by activating cyclin-dependent kinase-5 (Cdk5) in the pathogenesis of neurodegenerative disease." (PMID 33456665, 2020). "Hyperactivity of Cdk5/p25 contributes to the pathologic progression of several degenerative diseases by phosphorylation different relevant substrates, e.g., tau, neurofilament proteins, and β-amyloid precursor protein related to AD, MEF2D, synuclein, Parkin, and Prx2 related to PD." (PMID 29910724, 2018). "Moreover, Cdk5 has a substantial role in either direct or indirect interactions of those proteins common to, and critical in, different neurodegenerative diseases." (PMID 29301548, 2018). "Although the pathological activation of Cdk5 activity appears to be a contributing factor to the progression of some neurodegenerative diseases, we show that wild-type levels of Cdk5/p35 activity are necessary to support basal autophagy in the clearance of protein aggregates." (PMID 29227247, 2017). "In contrast to other cyclin-dependent kinases, CDK5 appears not to be directly involved in regulating progression through the cell cycle, but has been associated with neurogenesis, as well as with neurodegenerative disease." (PMID 22741533, 2012). "Cdk5 another proline region-specific kinase involved in hyperphosphorylation of tau hampers the ability of tau protein to bind and stabilize microtubules leading to the disruption of axonal transport and neuronal death-an important contributor to the pathology of neurodegenerative diseases like AD." (PMID 36158539, 2022). "AAV9-GFP-CIP alleviated not only motor symptoms but also non-motor symptoms in MPTP/p induced PD model mice, suggesting that inhibition of hyperactivity of Cdk5/p25 by CIP might be a new strategy for the treatment of neurodegenerative diseases including AD and PD." (PMID 29910724, 2018). "Therefore, the beneficial effects of PPARγ agonist treatment in neurodegenerative diseases could be due to inhibition of Cdk5 kinase activity and a subsequent reduction in tau phosphorylation." (PMID 24495352, 2014). "Since the discovery of Cdk5, numerous studies have revealed its multifunctional roles in important physiological processes, such as brain development and function, neuronal migration, synaptic plasticity, memory, learning, and neurodegenerative disease processes." (PMID 24359609, 2013). "Following an analysis of prediction results, we selected CDK5 and GSK-3β as potential target candidates for the investigated polyphenols, both kinases being involved in the physiopathology of neurodegenerative diseases and neuropathic pain." (PMID 38732407, 2024). "A series of abnormal S-nitrosated modified protein targets, including Drp1, Cdk5, PDI and Parkin, were found in neurodegenerative diseases." (PMID 32484546, 2020). "Compound 65 inhibited CK1, CDK5, GSK3β and SW620 (3.1 μM), KB-3-1 (2.0 μM), which are targets for treating neurodegenerative diseases." (PMID 31450856, 2019). "In addition to a deficit in NF axonal transport, increased Cdk5 activation and hyperphosphorylation of NFs might as well directly affect axonal degeneration in HSPB1 mutants as both events have been associated with neurodegenerative diseases." (PMID 23728742, 2013).
neurodegenerative disease (continued). "In addition, some CAMs have been shown to shuttle between FA and nucleus to regulate gene expression, including CDK5, ERK, GSK3B and COPS5 (JAB1) and members of the LIM family of proteins (PXN and Trip6), many of which have been implicated in the molecular pathology of neurodegenerative diseases." (PMID 22815752, 2012). "As the number of cellular processes regulated by Cdk5 increases, and Cdk5 is implicated in neuron-glia interaction as a part of etiology of neurodegenerative diseases, these findings will help us better understand the role of Cdk5 in development of non-neuronal brain cells." (PMID 23991155, 2013). "Moreover, chronic use of Cdk5 inhibitors in mice may induce seizure and behavioural changes, therefore Cdk5 inhibitors seem to be not suitable in neurodegenerative diseases." (PMID 38842132, 2024).